LGALS8 (galectin 8)
Description:
Beta-galactoside-binding lectin that acts as a sensor of membrane damage caused by infection and restricts the proliferation of infecting pathogens by targeting them for autophagy. Detects membrane rupture by binding beta-galactoside ligands located on the lumenal side of the endosome membrane; these ligands becoming exposed to the cytoplasm following rupture. Restricts infection by initiating autophagy via interaction with CALCOCO2/NDP52. Required to restrict infection of bacterial invasion such as S.typhimurium. Also required to restrict infection of Picornaviridae viruses. Has a marked preference for 3'-O-sialylated and 3'-O-sulfated glycans.
Synonyms: Gal-8; Po66-CBP; PCTA-1; PCTA1
Tractability: Small molecule: a structure with a bound ligand is known; a high-quality ligand is known. Antibody: the Human Protein Atlas places it where antibodies can reach. PROTAC: ubiquitination databases record sites on it; its protein half-life has been measured; a small molecule that binds it is known.
Target class: Other cytosolic protein
Gene: Protein-coding gene on chromosome 1 (236,518,000 to 236,552,981, forward strand). Ensembl gene ENSG00000116977.
Subcellular location: Cytoplasmic vesicle; Cytoplasm, cytosol
Subcellular location (Human Protein Atlas): Plasma membrane
Gene Ontology:
Molecular function: carbohydrate binding; integrin binding; protein binding
Biological process: cellular response to virus; lymphatic endothelial cell migration; xenophagy
Cellular component: cytoplasm; cytoplasmic vesicle; cytosol; membrane; extracellular region
Genetic constraint (gnomAD): Loss-of-function variants: 26 observed, 26.62 expected, observed/expected ratio (o/e) 0.98, 90% interval 0.71 to 1.36. The upper end of that interval is the gene's LOEUF score, 1.36, which puts it in group 5 of 6, group 1 being the genes least tolerant of losing a copy. Missense variants: 318 observed, 353.08 expected, observed/expected ratio (o/e) 0.9, 90% interval 0.82 to 0.99. Synonymous variants: 120 observed, 125.27 expected, observed/expected ratio (o/e) 0.96, 90% interval 0.82 to 1.12.
Homologues: Orthologues: chimpanzee LGALS8 (98% identical), macaque LGALS8 (95% identical), rabbit LGALS8 (87% identical), pig LGALS8 (85% identical), guinea pig LGALS8 (81% identical), mouse Lgals8 (79% identical), dog LGALS8 (78% identical), rat Lgals8 (78% identical), zebrafish lgals8a (51% identical), tropical clawed frog lgals8 (49% identical), zebrafish lgals8b (43% identical), Caenorhabditis elegans lec-3 (30% identical), and 6 more. Paralogues in human: LGALS4 (36% identical), LGALS9 (35% identical), LGALS9B (35% identical), LGALS9C (34% identical), LGALS12 (29% identical), LGALS3 (20% identical), LGALSL (17% identical), LGALS7 (15% identical), LGALS7B (15% identical), LGALS1 (14% identical), LGALS14 (12% identical), LGALS16 (12% identical), and 4 more.
Diseases named in the same sentence as LGALS8 in open-access papers:
LGALS8 is named in the same sentence as 118 diseases in open-access papers, as found by Europe PMC text mining. Sharing a sentence is not in itself a finding about the gene and the disease. The quoted sentences say what the papers report.
breast cancer (19 papers, 2014 to 2025). A primary or metastatic malignant neoplasm involving the breast. "Galectin-8, in particular, has been shown to be overexpressed in several types of cancer, including breast cancer, and its presence is associated with poor clinical outcomes." (PMID 39895791, 2025). "This suggests that elevated galectin-8 expression is associated with poorer prognosis in breast cancer patients." (PMID 39895791, 2025). "Within the TME, secreted galectin-8 binds to podoplanin on tumour-associated macrophages and lymphatic endothelial cells to promote lymphangiogenesis and lymph node metastasis in breast cancer mouse models." (PMID 37371482, 2023). "Further studies are warranted to explore the development of galectin-8 inhibitors and their efficacy in combination with existing therapies, particularly in clinical settings involving drug-resistant breast cancer." (PMID 39895791, 2025). "Given its multifaceted roles in promoting tumor progression and immune evasion, galectin-8 has emerged as a potential therapeutic target in breast cancer." (PMID 39895791, 2025). "At the protein level, galectin-8 expression was quantified using Z-values, representing standard deviations from the median across breast cancer samples." (PMID 39895791, 2025). "This analysis was conducted using data from The Cancer Genome Atlas (TCGA) to identify pathways influenced by galectin-8 expression and its potential role in breast cancer progression and therapy resistance." (PMID 39895791, 2025). "In this study, we aim to explore the expression levels of galectin-8 in drug-resistant breast cancer cell lines and investigate its potential role in promoting the MDR phenotype." (PMID 39895791, 2025). "Gene Set Enrichment Analysis (GSEA) further revealed that galectin-8 is involved in modulating drug resistance in breast cancer." (PMID 39895791, 2025). "Overall, this analysis emphasizes the critical role of galectin-8 in breast cancer progression, particularly in the aggressive basal-like subtype, and its involvement in driving both EMT and therapy resistance." (PMID 39895791, 2025). "By elucidating the molecular mechanisms by which galectin-8 contributes to drug resistance, we hope to identify new therapeutic strategies that target galectin-8 to overcome resistance in breast cancer." (PMID 39895791, 2025). "This confirmed that galectin-8 protein levels were elevated in breast cancer tissues, further supporting its role in cancer progression." (PMID 39895791, 2025). "Analysis revealed that galectin-8 protein levels were notably elevated in breast cancer tissues, particularly in stage 2 and stage 3 (mid-to-late stage) breast cancer." (PMID 39895791, 2025). "The results indicated significantly higher galectin-8 expression in breast cancer tissues compared to normal tissues." (PMID 39895791, 2025). "Given these roles, galectin-8 is thought to be a significant player in the development of drug resistance in breast cancer." (PMID 39895791, 2025). "We identified 6 autoantibodies that were present in mice prior to the development of mammary cancer: Pdhx, Otud6b, Stk39, Zpf238, Lgals8, and Vps35." (PMID 24886063, 2014). "Therefore, our findings underscore the potential significance of galectin-8 as a biomarker for breast cancer progression and prognosis." (PMID 39895791, 2025). "Therefore, in this study, we analyzed data from The Cancer Genome Atlas (TCGA) and identified a novel gene, galectin-8, which plays a critical regulatory role in breast cancer progression." (PMID 39895791, 2025). "Targeting galectin-8 could provide new therapeutic strategies to treat resistant forms of breast cancer, improving patient outcomes." (PMID 39895791, 2025). "First, we analyzed LGALS8 RNA expression levels across normal and breast cancer tissues." (PMID 39895791, 2025).
breast cancer (continued). "Furthermore, the study will evaluate the potential of galectin-8 as a prognostic marker, offering insight into its utility in predicting treatment responses and guiding therapy decisions in breast cancer management." (PMID 39895791, 2025). "Additionally, GSEA analysis revealed that galectin-8 plays a pivotal role in mediating therapy resistance, particularly in the context of drug-resistant breast cancer subtypes, such as TNBC." (PMID 39895791, 2025). "Therefore, our findings highlight the significant prognostic and therapeutic potential of galectin-8, emphasizing the importance of future research to explore targeted therapeutic strategies in breast cancer." (PMID 39895791, 2025). "This differential methylation may influence galectin-8 expression in breast cancer." (PMID 39895791, 2025). "Interestingly, galectin-8 has been found in malignant tumour tissues, especially in breast cancer." (PMID 37371482, 2023). "To ascertain the role and significance of galectin-8 in breast cancer, we utilized UALCAN for analyzing breast cancer patient data from The Cancer Genome Atlas (TCGA) database." (PMID 39895791, 2025). "Glycosylated PDPN combined with Galectin 8 (GAL8) can activate integrin-β1 and promote LEC adhesion and lymphangiogenesis, and this macrophage is closely related to lymphatic infiltration and lymphatic metastasis in breast cancer." (PMID 36831512, 2023). "There is no detailed analysis of all galectins and their specific effects in breast cancer and most galectins, like galectin-8 (Gal-8), have not been studied in detail." (PMID 32290551, 2020). "Pdhx was added as this antigen was identified in mice that eventually developed mammary cancer (unlike Lgals8) and Pdhx autoantibodies were significantly elevated at the earliest time points tested in the mice." (PMID 24886063, 2014). "Interestingly, the basal-like subtype of breast cancer, which is known for its poor prognosis and lack of hormone receptors, was highly enriched in the high galectin-8 expression group." (PMID 39895791, 2025).
lung carcinoma (13 papers, 2010 to 2025). "We also found that breast, gastric, liver, and lung cancer cell lines expressed both galectin-8 and B4GALT1." (PMID 39231945, 2024). "We then explored the impact of rGal-8 on the viability of CRC cells as a previous study demonstrated the pro-apoptotic effects of galectin-8 in H1299 lung carcinoma cells." (PMID 39231945, 2024). "Galectin-8 is highly expressed in breast, prostate, and lung cancer tissues and elevated serum levels of galectin-8 promote cellular interactions between cancer cells and vascular endothelium." (PMID 36873388, 2023). "The increase in the Galectin-8 gene (LGALS8) expression correlates with increased human lung cancer progression and metastasis." (PMID 31861875, 2019). "We analyzed the interaction of K-Ras4B and Galectin-8 and its impact on signal transduction, as well as cell proliferation and migration in pancreatic and lung carcinoma cells." (PMID 31861875, 2019). "All these findings show that galectin-1, galectin-3, and galectin-8 are the most abundantly expressed galectins while the expression of galectin-4, galectin-7, and galectin-9 is relatively low, both in tumor tissues and in different lung cancer cell lines." (PMID 25259711, 2014). "The presence of galectin-8 in lung tumor cells and its absence or very low levels in normal lung tissues permits the use of monoclonal antibodies (Po66) for the prevention and treatment of lung cancer." (PMID 23658855, 2010). "Some studies showed that the lung cancer could also be diagnosed by quantifying the galectin-8 expression level." (PMID 23658855, 2010). "Of the tandem-repeat galectins, galectin-8 showed no statistically significant change in these cancer types, but galectin-9 was increased in colon and lung cancer." (PMID 34638303, 2021). "In summary, our study uncovered Galectin-8 as a novel intracellular binding partner for K-Ras4B, which modifies K-Ras stability, ERK signaling, and migration and proliferation in pancreatic and lung carcinoma cells." (PMID 31861875, 2019).
ovarian carcinoma (11 papers, 2018 to 2025). A malignant neoplasm originating from the surface ovarian epithelium. "In addition to its role in TNBC, galectin-8 has been implicated in other malignancies such as colorectal and ovarian cancers, where it contributes to immune evasion, tumor cell invasion, and metastasis." (PMID 39895791, 2025). "In the present study, however, we revealed that increased expression of LGALS8 mRNA predicted a favorable OS in all patients with ovarian cancer, as well as in patients with all stages." (PMID 33854625, 2021). "The different phenomeon in ovarian cancer may be due to that tumor microenvironment in ovarian caner likely has a promoting effect on the tumor suppressor function of LGALS8." (PMID 33854625, 2021). "Regarding with different clinical stages of ovarian cancer, it was observed that elevated LGALS8 and LGALS10 mRNA expression predicted a better OS in patients with stages I+II as well as with stages III+IV, and LGALS4 predicted a better OS in patients with stages I+II." (PMID 33854625, 2021). "Galectin-8 staining could be evaluated in 143 ovarian cancer samples." (PMID 29361803, 2018). "LGALS1, LGALS3, LGALS4, LGALS8 and LGALS9 were found to be overexpressed in ovarian cancer patients." (PMID 37238197, 2023). "LGALS1, LGALS3, LGALS4, LGALS8, and LGALS9 were found to be mostly overexpressed in ovarian carcinoma patients with the following percentage: 78.6%, 92.9%, 66.1%, 87.5%, and 85.7% respectively." (PMID 36050693, 2022). "In total patients with ovarian cancer, LGALS4, LGALS8, LGALS10 and LGALS13 mRNA levels were related to a better OS, and LGALS1 to a worse OS." (PMID 33854625, 2021). "In the present study, the mRNA expression of five galectins (LGALS1, LGALS3, LGALS4, LGALS8, and LGALS9) is explored in the tumor samples of 56 ovarian carcinoma patients, and the expression fold change was calculated in comparison to 26 adult females with normal ovaries." (PMID 36050693, 2022). "Galectin-8 was repeatedly studied in different types of cancer, but to the best of our knowledge, galectin-8 expression was not investigated in ovarian carcinomas patients." (PMID 36050693, 2022). "Notably, the staining score of LGALS8, LGALS10 and LGALS13 in ovarian cancer tissues were 3.04±1.24, 1.26± 0.65 and 1.52 ± 0.58, respectively, which were all lower than those in normal ovarian tissues (9.04±0.84, 7.24±1.69, 8.67±0.78) (all P<0.05)." (PMID 33854625, 2021). "The protein level of LGALS1, LGALS4, LGALS8, LGALS10 and LGALS13 in ovarian cancer cell lines were all decreased compared with those in the normal ovarian cell (all P<0.05)." (PMID 33854625, 2021).
rheumatoid arthritis (11 papers, 2012 to 2025). A chronic, systemic autoimmune disorder characterized by inflammation in the synovial membranes and articular surfaces. "Interestingly, a clinical association of a single nucleotide polymorphism in the coding region of the galectin-8 gene (that is, the F19Y substitution) was recently revealed with rheumatoid arthritis." (PMID 24289744, 2013). "Antibodies to Lgals8 have been identified in a variety of autoimmune diseases including systemic lupus erythematosis and rheumatoid arthritis and may play a role in regulating autoimmune inflammation." (PMID 24886063, 2014). "Galectin-8 is widely expressed in human tissues and tumors and, to emphasize potential orthopedic relevance, is produced and secreted by human synovial fluid cells in patients with rheumatoid arthritis." (PMID 24289744, 2013). "Anti-galectin-4 and -8 aAbs were found in SLE and rheumatoid arthritis (RA); anti-galectin-7 aAb in SLE; and anti-galectin-8 and -9 aAbs in SLE and RA." (PMID 35008499, 2021).
colon cancer (9 papers, 2010 to 2025). "These authors observed a significant prognostic value associated with galectins-1,3, and -4 in Dukes A and B colon tumors and galectin-8 in Dukes C and D." (PMID 23658855, 2010). "A similar study demonstrate that not only galectin-3 but also galectin-1 expression levels correlate with the degree of dysplasia, suggesting that galectin-1 is related to malignant progression, while galectin-8 has been associated with suppressor activity in colon cancer." (PMID 23658855, 2010). "Quite the opposite behavior was observed for galectin-8 in colon cancer, where its expression decreased compared with healthy tissue, and galectin-8 acted as the suppressor of tumor cell migration." (PMID 40649198, 2025). "Galectin-8 was observed to be increased more in male patients with colon cancer compared to female patients with colon cancer." (PMID 34638303, 2021). "The effects of galectin-8 are poorly understood, but it has been shown to possibly promote metastasis of colon cancer by enhancing malignant cell adhesion to endothelium." (PMID 34638303, 2021). "Furthermore, in another study, galectin-8 coated on plastic markedly decreased the migration of two types of colon cancer cells, HCT-15 and CoLo-201." (PMID 39337581, 2024). "Specifically, a study showed that galectin-8 (as well as galectins-2 and -4) contributes to the expression of IL-6, a known promotor of cell adhesion, in serum samples from patients with breast and colon cancer." (PMID 34638303, 2021).
viral infection (8 papers, 2016 to 2023). "Four signaling pathways (interferon signaling, BRCA1/DNA damage response, PKR/INF induction and LGALS8), which may control the viral infection, are clearly associated with the BEN+ phenotype in SMs." (PMID 27280726, 2016). "Endosomes permeated by VP4 are recognized by galectin-8 (LGALS8), targeting them for autophagic degradation, thus restricting virus infection." (PMID 33499355, 2021). "In addition, galectin 8 suppresses viral infection by autophagic degradation of the viral RNA genome." (PMID 32967959, 2020). "In addition, some of the genes involved in endothelial cell migration (ETS1, LGALS8, and PDCD10) are also known to be associated with perturbations during viral infection." (PMID 33240937, 2020).
glioblastoma (7 papers, 2016 to 2025). The most malignant astrocytic tumor (WHO grade IV). "This region covers part of the LGALS8 gene, a galectin previously implicated in migration and proliferation of U87 glioblastoma cells." (PMID 31392989, 2019). "For example, the results from one study suggested that galectin-8 (along with galectin-1 and -3) may be associated with the tumor astrocyte invasion of the brain parenchyma, where it was shown that these galectins stimulated glioblastoma cell migration in vitro." (PMID 39337581, 2024). "For example, in glioblastoma U87 cells, exogenously added galectin-8 induced directional migration." (PMID 39337581, 2024). "Galectin-8 is one of the galectins highly expressed in glioblastoma cells." (PMID 27459991, 2016).
prostate carcinoma (7 papers, 2017 to 2024). A carcinoma that arises from epithelial cells of the prostate gland. "In this study we silenced Galectin-8 in two human prostate cancer cell lines, PC3 and IGR-CaP1, and designed a pre-clinical experimental model that allows monitoring the pathology from its early steps to the long-term metastatic stages." (PMID 28591719, 2017). "Two decades ago, Galectin-8 was described as a prostate carcinoma biomarker since it is only expressed in the neoplastic prostate, but not in the healthy tissue." (PMID 28591719, 2017). "Collectively, our results highlight Galectin-8 as a potential target for anti-metastatic therapy against prostate cancer." (PMID 28591719, 2017).
autoimmune disease (6 papers, 2012 to 2023). A disorder resulting from loss of function or tissue destruction of an organ or multiple organs, arising from humoral or cellular immune responses of the individual to their own tissue constituents. "Galectin-8 (Gal-8) is a member of a glycan-binding protein family that regulates the immune system, among other functions, and is a target of antibodies in autoimmune disorders." (PMID 28650992, 2017).
colorectal cancer (5 papers, 2022 to 2025). A primary or metastatic malignant neoplasm that affects the colon or rectum. "ELN was predicted to have overexpression in colorectal cancer but was under-expressed in the majority of the other types, while LGALS8 was found to be downregulated in colorectal cancer and overexpressed in all other types." (PMID 38544823, 2024). "Furthermore, expression of LGALS8 in lung, prostate and colorectal cancer is considered to have potential prognostic capabilities, particularly in advanced stages in patients with distant metastases." (PMID 38544823, 2024).
COVID-19 (5 papers, 2022 to 2024). A disease caused by infection with severe acute respiratory syndrome coronavirus 2. "Plasma ACBP concentrations positively correlated with ATG 3, ATG5 and LC3II, but negatively correlated with ATG4B, BECN1 and galectin 8 in participants with COVID-19." (PMID 39835130, 2024).